SPRED1 (sprouty related EVH1 domain containing 1)
Diseases named in the same sentence as SPRED1 in open-access papers (continued):
Sharing a sentence is not in itself a finding about the gene and the disease.
melanoma (27 papers, 2014 to 2025). A malignant, usually aggressive tumor composed of atypical, neoplastic melanocytes. "NF1-mutant melanomas preferentially harbored alterations in RASopathy genes, with SPRED1, RASA2, and RASSF2 being identified as significantly mutated genes within the subtype." (PMID 38758740, 2024). "NF1-mutant melanomas in our cohort were enriched for SV events affecting SPRED1 and RAF1, the latter of which has been implicated in activating fusion events in cutaneous melanoma and was observed to be enriched in TWT tumors." (PMID 38758740, 2024). "St.rikingly, some observations uncovered that Sprout-related EVH1 domain-containing protein 1 (SPRED1) loss promotes cell proliferation in KIT-driven melanoma, as a result of SPRED1's function as a tumor suppressor in the MAPK pathway." (PMID 37773078, 2023). "Julien’s team even experimentally confirmed SPRED1 loss was a driver of mucosal melanoma using zebrafish modeling." (PMID 37831226, 2023). "More recently, the relevance of the zebrafish model in melanoma research was highlighted by the identification of the loss of SPRED1 in mucosal melanoma and the role of anatomical position in determining oncogenic specificity." (PMID 35883768, 2022). "As an example, this technique was used to investigate SPRED1 function as a tumor suppressor in the context of KIT mutations in mucosal melanoma." (PMID 35713744, 2022). "SPRED1 loss has been found in patients whose melanoma had developed resistance to MAPK-targeted treatment." (PMID 34804979, 2021). "SPRED1 deficiency enhanced melanoma cell proliferation under mutant BRAF inhibition via the reactivation of MAPK activity." (PMID 34804979, 2021). "A modified version of the MiniCoopR approach was developed to test the effect of SPRED1 loss on melanoma initiation." (PMID 32455885, 2020). "MAPK inhibition in SPRED1-deficient melanomas could therefore be a therapeutic hint and again proves the power of zebrafish modeling to investigate genetic interactions in cancer pathways." (PMID 35713744, 2022). "In human melanoma cell lines, SPRED1 levels are modulated via the RAS pathway, suggestive of a negative feedback loop similar to that regarding SPROUTY proteins." (PMID 35234863, 2022). "Our own group recently discovered that the negative regulator of RAS, SPRED1, is a major tumor-suppressor gene deleted in >26% of mucosal melanomas." (PMID 35234863, 2022). "For example, acral and mucosal melanomas have fewer BRAF mutations but more frequent KIT mutations, amplifications of CCND1, CDK4, and MDM2, and deletion of SPRED1." (PMID 35706047, 2022). "Since KIT mutations predominate over BRAF or NRAS mutations in mucosal melanomas, this result suggests a special cooperativity between KIT gain of function and SPRED1 loss." (PMID 32455885, 2020). "In a search for genetic alterations in mucosal melanomas, SPRED1, a negative regulator of MAPK signaling, was found inactivated in 37% of the tumors." (PMID 32759814, 2020). "SPRED1 (sprouty-related, EVH1 domain containing protein 1) loss was found as a new driver in mucosal melanoma and the majority of cases with SPRED1 loss were genetically “triple wild-type” tumors." (PMID 31731811, 2019). "In summary, our data reveal a complex RTK-associated and SPRED1/2-mediated feedback network which can be relieved by MEK inhibition and thereby protects from DNA damage induced apoptosis in melanoma cells." (PMID 24970815, 2014).
melanoma (continued). "Although mutations in SPRED1 and KIT are relatively weaker activators of the RAS pathway compared to the BRAFV600E or NRASQ61R mutants, they frequently occur together to drive mucosal melanoma." (PMID 35234863, 2022). "But, whilst mutant NF1 is known to cooperate with RASopathy genes (RASA2, PTPN11, SOS1, RAF1 and SPRED1) in melanoma and although NF1 is found to be frequently mutated (25–30%) in melanomas harbouring wild-type BRAF and NRAS, it is curious that melanoma is not a tumour type associated with NF1." (PMID 28637487, 2017). "In addition, all 26 NF1 mutant BRAF-RAS wild-type melanomas carried mutations in other known RASopathy genes, including RASA2, PTPN11, SOS1, RAF1 and SPRED1." (PMID 28637487, 2017). "However, we also observed the downregulation of SPRY2 and 4 as well as SPRED1 and -2 in a melanoma cell line (451Lu) which is MEK inhibitor sensitive and does not display enhanced AKT activation by PD." (PMID 24970815, 2014). "Interestingly, Spred1 (whose product also acts as negative regulator of the Ras pathway and is a recently discovered melanoma tumor suppressor) ranked within the top 10 CIS and exhibited a disruptive piggyBac insertional pattern, suggesting Spred1 acts as a novel tumor suppressor in glioma." (PMID 32727536, 2020). "However, while NF1 and SPRED1 mutations typically co-occur in cutaneous melanoma, in our study of mucosal melanomas, most SPRED1 aberrations identified in WGS samples (11/13) occurred in NF1 wild-type samples, with only two SVs in SPRED1 co-occurring with NF1 mutations." (PMID 31320640, 2019). "After sequencing human mucosal melanomas, they learned that sprout related EVH1 domain containing 1 (SPRED1), a negative regulator of the MAPK pathway, is inactivated in 37% of these tumors." (PMID 32455885, 2020). "NF1-mutant melanomas were significantly associated with non-duplication SV events in two RASopathy genes, RAF1 and SPRED1 (Fisher’s exact, OR = 5.03, 95% CI = 1.46–16.42, P = 4.8 × 10–3), the latter of which has also been identified as a significantly mutated gene exclusive to NF1-mutant melanomas." (PMID 38758740, 2024). "On the other hand CYT-low metastatic melanomas had recurrent amplifications in loci 5p15.33 (TERT), 6p25.1 (CDYL), 7p22.2 (RAC1), 12q15 (MDM1) and recurrent deletions in 5q31.2 (CTNNA1, FGF1), 11q22.3 (FDX1, RDX, ZC3H12C), and 15q14 (RASGRP1, CSNK1A1P1, SPRED1)." (PMID 33779796, 2021). "Alterations of upstream effectors of RAS, such as NF1 or SPRED1, in mucosal melanomas could play this role, but there is currently not enough extensive genomic data on mucosal melanoma to confirm this hypothesis." (PMID 31398831, 2019).
RASopathy (20 papers, 2014 to 2025). Developmental syndromes caused by germline mutations (or in rare cases by somatic mosaicism) in genes that alter the Ras subfamily and mitogen-activated protein kinases that control signal transduction. "Primary RASopathy gene SPRED1 is a negative regulator of the pathway; MAP3K2 encodes MEK kinase 2; RAPGEF2 encodes a Ras activator thought to control developmental neuronal migration in the cortex and formation of the corpus callosum." (PMID 28076348, 2017). "As expected, RAS proteins are the ones with the highest number of associations, although RASopathies related to SPRED1, MEK1/2, PTPN11, FGFR3 and SPRY1 may regulate RAS signaling differently, affecting primarily the classical RAS versus RRAS signaling." (PMID 34229750, 2021). "Our study phenotyped Spred1-/- mice across a panel of behavior tests linked to social functioning, with the aim of identifying robust, reproducible phenotypes that could be used for screening drugs that modulate behavior in RASopathy models." (PMID 34311771, 2021). "Specific RASopathy-associated genes were intentionally excluded, notably NF1 (HGNC:7765) and SPRED1 (HGNC:20249)." (PMID 40496714, 2025). "Since a diagnosis of NF1 or LS would change patient management, the NF1 and SPRED1 genes should be included on all to Noonan spectrum disorder/RASopathy NGS gene panels, including those used prenatally." (PMID 32107864, 2020). "The addition of the NF1 and SPRED1 genes to Noonan spectrum and RASopathy gene panels should reduce the time to diagnosis for such individuals and allow for appropriate medical management." (PMID 32107864, 2020). "Cost‐benefit considerations support adding the NF1 and SPRED1 to the Noonan spectrum disorder/RASopathy NGS gene panels." (PMID 32107864, 2020). "Adding the NF1 and SPRED1 genes to Noonan spectrum disorder/RASopathy NGS gene panels modestly increases clinical diagnoses without significantly increasing the VUS burden." (PMID 32107864, 2020). "Since a diagnosis of NF1 or LS would change patient management, NF1 and SPRED1 should be included on all Noonan spectrum disorder/RASopathy NGS gene panels." (PMID 32107864, 2020). "The SPRED1 gene encodes a negative regulator of the RAS‐MAPK pathway, like neurofibromin, and thus may be considered a RASopathy." (PMID 40437629, 2025). "Hence, many clinical laboratories now offer large RASopathy panels that include the NF1 and SPRED1, and this study quantifies the diagnostic yield of such testing." (PMID 32107864, 2020). "Sequencing of all 14 RASopathy‐associated genes in the 505 patients in the validation cohort identified 11 (2%) patients with disease‐causing variants and 15 (3%) patients with a VUS (n = 11) or VUS‐likely benign (n = 4) in the NF1 or SPRED1 genes." (PMID 32107864, 2020). "Furthermore, it also enabled us to determine if there were differences in phenotype- or treatment efficacy compared to other mouse models of RASopathies caused by mutations in up-stream regulators of HRAS protein, such as NF1, SHP2/PTPN11, and SPRED1." (PMID 28455524, 2017). "In addition, we verified by exomeanalysis that the patient did not have any pathogenic variants in the genes associatedwith Noonan Syndrome and other rasopathies (PTPN11,SHOC2, KRAS, CBL,SOS1, RAF1, HRAS,NRAS, RASA1, SPRED1,BRAF, MAP2K1, MAP2K2, RIT1 andRRAS)." (PMID 27561113, 2016). "Those RASopathy genes with ubiquitous or enriched GABAergic expression compared with excitatory cells, including Hras, Kras, Mapk1, Ptpn11, Sos1 and Spred1, may be of particular relevance." (PMID 37254876, 2023). "Indeed, the defective function of an increasing number of proteins (i.e., neurofibromin, LZTR1, SPRED1 and SPRED2) provides evidence of multiple circuits implicated in the negative control of RAS function as a recurrent theme of RAS‐MAPK signaling upregulation in RASopathies." (PMID 36394128, 2022).
RASopathy (continued). "The recessive inheritance of this new RASopathy further indicates a differential requirement of SPRED2 and SPRED1 function in developmental processes." (PMID 36394128, 2022). "In conclusion, social behavior phenotypes can be modelled robustly in Spred1-/- mice, indicating its validity as a model for studying ASD in RASopathies." (PMID 34311771, 2021). "Three patients in the ESTAND cohort had findings in pleiotropic genes SPRED1, NF1, and LZTR1 linked to developmental syndromes referred to as RASopathies, including various cancerous and non-cancerous tumors as part of the respective syndromic phenotype." (PMID 40060932, 2025). "If the clinical phenotype is not typical, either multi-gene panels (that include NF1, SPRED1 genes, or rasopathy multigene panel) or comprehensive genomic testing (as exome sequencing or genome sequencing) may be considered." (PMID 39860457, 2025). "Further analysis of the exome data for this patient did not reveal any variants in SPRED1, NF2 or other genes associated with RASopathies that could explain the phenotype." (PMID 37012328, 2023). "Social dominance has not yet been examined in other RASopathy mouse models, and our results in Spred1-/- mice suggest this test might enable detection of social phenotypes in models for which social approach phenotypes are not seen." (PMID 34311771, 2021). "Therefore, despite the modest increase in molecular diagnosis in our study (increased from 23.5% to 25.7% in the validation cohort with an overall positive rate = 3.2% (17/533) for both cohorts), patients with a suspected RASopathy should be tested on an NGS panel that includes the NF1 and SPRED1." (PMID 32107864, 2020).
neurofibromatosis type 1 (11 papers, 2011 to 2026). A clinically heterogeneous, neurocutaneous genetic disorder characterized by cafe-au-lait spots, iris Lisch nodules, axillary and inguinal freckling, and multiple neurofibromas. "A recent study demonstrates that SPRED1 interacts with neurofibromin, a protein encoded by NF1, mutation of which leads to neurofibromatosis type 1 (NF1) syndrome." (PMID 32175275, 2020). "Constitutional loss-of-function mutations in the SPRED1 gene cause a rare phenotype referred as neurofibromatosis type 1 (NF1)-like syndrome or Legius syndrome, consisting in multiple café-au-lait macules, axillary freckling, learning disabilities, and macrocephaly." (PMID 26909356, 2015).
breast carcinoma (7 papers, 2016 to 2025). "These included regulators of the RAS MAPK pathway, including SPRED1-encoding Spred-1 and MAP2K5, both of which are known to reduce tumor growth, although the latter promotes invasiveness in breast cancer." (PMID 38473331, 2024). "The miR-196a up regulation by estrogen enhances the development of breast cancer via targeting the SPRED1." (PMID 36831624, 2023). "In addition, SPRED1 is thought to be a regulator in several tumors, including gastric cancer and breast cancer." (PMID 38233508, 2024). "In addition, miR-133a targeting of EGFR, miR-200c and miR-30c targeting of KRAS, miR-148b targeting of NRAS, miR-7 targeting of RAF1, miR-206 targeting of RASA1 and miR-21 targeting of SPRED1 have been reported in breast cancer cells." (PMID 27462780, 2016). "SPRED1, as a negative regulator of the MAPK pathway, influences tumor growth and metastasis in breast cancer." (PMID 38217548, 2024).
leukemia (6 papers, 2019 to 2025). A malignant (clonal) hematologic disorder, involving hematopoietic stem cells and characterized by the presence of primitive or atypical myeloid or lymphoid cells in the bone marrow and the blood. "The downregulation of miR-126 in leukemia cells was linked to the phosphorylation of Sprouty-related EVH1-domain-containing 1 (SPRED1) by BCR-ABL, which inhibited the RAN–exportin-5–RCC1 complex responsible for miRNA maturation." (PMID 40376111, 2025). "With the present study, for the first time, we assessed the ole of Sprouty1 in a rather large cohort of adult AML patients, as previously observed for SPRED1 in pediatric leukemia." (PMID 31277439, 2019). "In addition, the previous study of pediatric leukemia showed that SPRED1 expression appeared to be significantly decreased in AMLs and T-ALL, but normal in B-ALL." (PMID 32175275, 2020). "In order to define the clinical features as well as the prognostic significance of SPRED1 in leukemia, in the present study, we determined the expression of SPRED1 in adult AML and analyzed the association of SPRED1 expression with clinical parameters, disease status, and survival." (PMID 32175275, 2020). "It suggests that SPRED1 plays a vital role in the progression of leukemia." (PMID 32175275, 2020).
mucosal melanoma (5 papers, 2019 to 2023). A melanoma that arises from a mucosal site. "Our multi-tool analysis of SMGs identified SPRED1 as a driver in mucosal melanoma, which was mutated in tumors from a variety of anatomical sites." (PMID 31320640, 2019). "At present, some studies have found that mutations that activate SF3B1 and KIT, the deletion of CDKN2A, PTEN, or SPRED1, and the amplification of CDK4, TERT, KIT, MDM2, or CCND1 are common in mucosal melanoma." (PMID 38065883, 2023).
acute myeloid leukemia (4 papers, 2020 to 2022). Acute myeloid leukemia (AML) is a group of neoplasms arising from precursor cells committed to the myeloid cell-line differentiation. "SPRED1 (Sprouty-related, EVH1 domain-containing protein 1) has been reported as a tumor repressor in paediatric acute myeloblastic leukaemia." (PMID 35885958, 2022). "Sprouty-related, EVH1 domain-containing protein 1 (SPRED1) has been identified as a novel tumor suppressor gene in acute myeloid leukemia (AML)." (PMID 35359401, 2022). "We report herein that Sprouty-Related EVH1 Domain-Containing Protein1 (SPRED1) is downregulated and a prognostic biomarker in adult acute myeloid leukemia (AML)." (PMID 32175275, 2020). "Moreover, a recent study suggests that SPRED1 is a tumor suppressor and is downregulated in pediatric acute myeloid leukemia (AML)." (PMID 32175275, 2020).
Anxiety (4 papers, 2021 to 2023). Intense feelings of nervousness, tension, or panic often arise in response to interpersonal stresses. "Among the genes coexpressed with Fmr1, genes Spred1 and Pten have already been characterized as genes associated with an abnormal anxiety-related response (Rat Genome Database)." (PMID 36769363, 2023). "The results showed that Gfap, Rhog, Gnai2, Ppp1r1b, and Uqcrh were specifically dysregulated in the prefrontal cortex of the depression-susceptible group, while Tubb6, Urod, Cul1, Spred1, and Gpcpd1 were specifically dysregulated in the anxiety-susceptible group." (PMID 33627638, 2021). "miR-144-3p targets a number of genes including Pten, Spred1, EGFR, Nrf2, AQP1, NGF, Brg1 and Notch, which are implicated in the stress response, anxiety and mood stabilizer treatment." (PMID 34674715, 2021).
diabetes (4 papers, 2019 to 2023). "In diabetes, SPRED1 was also reported to be a therapeutic target in endothelial microparticle‐mediated vascular endothelial cell repair, and this mechanism was abrogated in glucose‐damaged endothelial microparticles." (PMID 37646268, 2023). "One of the miRNAs most strongly linked to diabetes was miR-126, which was abundant in endothelial cells and helped maintain their health and the integrity of blood vessels by suppressing negative regulators of the VEGF pathway, such as SPRED1 and PIK3R2/p85-β." (PMID 38067127, 2023).
hepatocellular carcinoma (4 papers, 2018 to 2025). A malignant tumor that arises from hepatocytes. "This study establishes TTC36 as a pivotal tumor suppressor in hepatocellular carcinoma that orchestrates a previously unrecognized TTC36/YBX3/SPRED1 signaling axis which suppresses Ras/MAPK pathway to constrain tumor proliferation." (PMID 41208883, 2025). "SPRED1 negatively regulated signaling pathways contributing to hepatic carcinoma progression, and its overexpression inhibited the malignant features of hepatoma cells." (PMID 36629984, 2023). "Expression levels of SPRED1 were demonstrated to be down-regulated in hepatocellular carcinoma (HCC) and overexpression of SPRED1 inhibited HCC proliferation, migration and invasion." (PMID 29685157, 2018).
neurofibroma (4 papers, 2020 to 2026). An intraneural or extraneural neoplasm arising from nerve tissues and neural sheaths. "No freckling or neurofibroma was found in three probands, and no NF1 or SPRED1 mutation was detected by genetic analysis." (PMID 36438053, 2022).
endothelial dysfunction (3 papers, 2020 to 2022). In vascular diseases, endothelial dysfunction is a systemic pathological state of the endothelium (the inner lining of blood vessels) and can be broadly defined as an imbalance between vasodilating and vasoconstricting substances produced by (or acting on) the endothelium. "ICA II could ameliorate endothelial dysfunction by regulating the MAPK pathway via miR-126/SPRED1 in HCECs exposed to a diabetic-like environment." (PMID 35846993, 2022).